HSPA2 (heat shock protein family A (Hsp70) member 2)
Diseases named in the same sentence as HSPA2 in open-access papers (continued):
Sharing a sentence is not in itself a finding about the gene and the disease.
cervical cancer (6 papers, 2013 to 2023). A primary or metastatic malignant neoplasm involving the cervix. "We also examined the effects of HSPA2 knockdown on the malignant phenotype of selected breast and cervical cancer cell lines that have been previously identified as dependent on the HSPA2 protein." (PMID 32987811, 2020). "HSPA2 gene silencing could affect the motility and invasiveness of urothelial and cervical cancer cell lines (PMID: 19914824)." (PMID 37745978, 2023). "On the contrary, we observed negligible effects of HSPA2 depletion on the growth, adhesion, migration, and invasion of NSCLC, as well as of breast and cervical cancer cells." (PMID 32987811, 2020). "Our data presented in this article contradict the current belief of the essential role of HSPA2 chaperone and show that HSPA2 is not crucial for maintenance of the malignant phenotype of lung, breast, and cervical cancer cells." (PMID 32987811, 2020). "In this work, we showed that lung, breast, and cervical cancer cells are not dependent on HSPA2 in terms of their ability to proliferate, form colonies, migrate, invade, and adhere to the ECM components." (PMID 32987811, 2020). "The data presented in this article clearly show that HSPA2 does not promote the malignant phenotype of NSCLC, breast, and cervical cancer cells." (PMID 32987811, 2020). "In this study, we compared the phenotypic effects of HSPA2 deficit in non-transformed human bronchial epithelial cells (HBEC), and in lung, breast, and cervical cancer cells." (PMID 32987811, 2020).
lung carcinoma (6 papers, 2015 to 2023). "HSPA2, whose cellular functions in lung cancer are unclear, was higher expressed (1.4 fold in A549 cells and 1.2 fold in H226 cells) in JAG1 transfectants compared with control cells." (PMID 26930648, 2016). "In summary, our findings are the first to form the basis that JAG1 serves as a prognostic biomarker and JAG1/HSPA2 axis contributes to the lung cancer malignancy." (PMID 26930648, 2016). "In conclusion, this is the first study that demonstrated that JAG1 might act as a potential prognostic marker and JAG1/HSPA2 axis mediates lung cancer malignancy at least partly." (PMID 26930648, 2016). "Finally, we would like to test whether JAG1 was colocalized with HSPA2 and fluorescent immunohistochemistry staining was performed in lung cancer patients’ tissue section." (PMID 26930648, 2016). "Although JAG1 and HSPA2 were only partially colocalized in patients’ tumor biopsy, the regulation of HSPA2 by JAG1 could be an important find for lung cancer cell malignancy." (PMID 26930648, 2016). "However, neither HSPA1 nor HSPA2 were necessary to provide protection against MA in lung cancer cells." (PMID 34200371, 2021).
non-small cell lung carcinoma (6 papers, 2015 to 2022). A group of at least three distinct histological types of lung cancer, including non-small cell squamous cell carcinoma, adenocarcinoma, and large cell carcinoma. "High expression of HSPA2 have been associated with shorter overall survival in stage I-II of non-small cell lung carcinoma patients." (PMID 31101846, 2019). "Previously, we showed that both stress-inducible HSPA1 and testis-enriched HSPA2, highly homologous members of the HSPA (HSP70) family, are often overexpressed in non-small cell lung carcinoma (NSCLC)." (PMID 31591429, 2019). "In our earlier studies we found that prognostic values of HSPA2 and HSPA1 expression in patients with primary non-small cell lung carcinoma (NSCLC) are opposite." (PMID 31591429, 2019).
asthenozoospermia (4 papers, 2019 to 2024). "Given that an aberrant HSPA2 level was significantly associated with asthenozoospermia, our data support the hypothesis that humancircBOULE exerts its sperm function by regulating sperm HSPA2 levels, similar to its counterpart in flies and mice." (PMID 38808558, 2024).
esophageal squamous cell carcinoma (4 papers, 2013 to 2022). Esophageal squamous cell carcinoma (ESCC) is a type of esophageal carcinoma (EC) that can affect any part of the esophagus, but is usually located in the upper or middle third. "Similar to our study, Zhang et al22 stated that HSPA-2 overexpression was associated with pT, clinical stage, pN, and recurrence in esophageal SCC." (PMID 35703525, 2022). "HSPA2 was also overexpressed in esophageal squamous cell carcinoma and was significantly associated with primary tumor, TNM stage, lymph node metastases and recurrence resulting in shorter DFS and OS37." (PMID 31101846, 2019).
pancreatic cancer (4 papers, 2015 to 2020). "In this study, we therefore assessed the messenger RNA (mRNA) expression of HSPA2 in a series of pancreatic cancer specimens and investigated its associations with clinicopathological parameters and overall survival in patients with pancreatic cancer." (PMID 25890028, 2015). "More importantly, we proved that HSPA2 mRNA expression was significantly associated with overall survival of patients with pancreatic cancer." (PMID 25890028, 2015). "The association between HSPA2 mRNA expression and overall survival of pancreatic cancer patients was investigated by Kaplan-Meier analysis and log-rank test." (PMID 25890028, 2015). "Our results suggest that high expression of HSPA2 in pancreatic cancer is associated with poor overall survival and that HSPA2 may be served as a prognostic marker for pancreatic cancer." (PMID 25890028, 2015). "For a more comprehensive insight into the clinical value of HSPA2 in pancreatic cancer, we performed a real-time quantitative RT-PCR assay to explore the mRNA expression level of HSPA2 as well as to investigate its association with clinicopathological features of pancreatic cancer patients." (PMID 25890028, 2015). "Univariate analysis demonstrated that TNM stage (P = 0.013), the status of lymph node metastasis (P = 0.040) and vascular invasion (P = 0.017), and HSPA2 mRNA expression level (P = 0.007) were significantly associated with overall survival of pancreatic cancer patients." (PMID 25890028, 2015). "Our results suggest that overexpression of HSPA2 in pancreatic cancer is associated with aggressive progression and poor prognosis and that HSPA2 may be served as a prognostic marker." (PMID 25890028, 2015). "HSPA2 mRNA expression was detected in 104 pairs of pancreatic cancer and adjacent normal tissues by real-time quantitative RT-PCR." (PMID 25890028, 2015). "In summary, we have reported the differential expression of HSPA2 in pancreatic cancer and adjacent normal tissues." (PMID 25890028, 2015). "HSPA2 mRNA expression levels were significantly higher in the cancerous tissues of patients with IIA-IIB stage pancreatic cancer than those with IA-IB stage (P = 0.006)." (PMID 25890028, 2015). "Pancreatic cancer patients with low HSPA2 mRNA expression level had longer overall survival time than those with high HSPA2 mRNA expression level (log-rank test: P =0.019)." (PMID 25890028, 2015). "After normalization to β-actin expression levels, the expression level of HSPA2 in pancreatic cancer tissues (3.9 ± 0.8) was significantly higher than that in adjacent normal tissues (1.1 ± 0.4) (P < 0.001)." (PMID 25890028, 2015). "HSPA2 mRNA was significantly overexpressed in pancreatic cancer tissues (3.9 ± 0.8) than in adjacent normal tissues (1.1 ± 0.4) (P < 0.001)." (PMID 25890028, 2015). "Importantly, consistent conclusions on HSPA2 as a marker of poor outcome for pancreatic cancer patients were obtained analyzing HSPA2 expression in primary tumors at mRNA level." (PMID 32560263, 2020). "In support of this, Kaplan-Meier analysis of overall survival showed that patients whose tumors had higher HSPA2 expression tend to have a significantly worse overall survival, indicating that a high HSPA2 level is a marker of poor prognosis for patients with pancreatic cancer." (PMID 25890028, 2015). "However, little is known about the expression and clinical significance of HSPA2 in pancreatic cancer." (PMID 25890028, 2015). "However, the status of HSPA2 expression and its prognostic significance in pancreatic cancer remain unknown." (PMID 25890028, 2015). "However, whether HSPA2 is highly expressed in pancreatic cancer is unclear." (PMID 25890028, 2015). "Quantitative reverse transcriptase ploymerase chain reaction (qRT-PCR) was applied to examine HSPA2 messenger RNA (mRNA) expression in 104 pairs of pancreatic cancer tissues and adjacent noncancerous tissues." (PMID 25890028, 2015).
bladder cancers (3 papers, 2015 to 2023). "HSPA2, one DNA methylation biomarker, was identified to be a reliable, noninvasive, and cost-effective diagnostic tool in bladder carcinoma." (PMID 37745978, 2023). "In genome-wide studies designed to unveil new bladder cancer-specific epigenetic markers, the HSPA2 gene was found among the most frequently methylated genes both in bladder cancer cell lines and in primary bladder tumors, but not in normal urothelial tissue." (PMID 25344376, 2015). "While hypermethylation-related repression of the HSPA2 gene in primary bladder tumors has been reported, others found the HSPA2 gene to be highly expressed in bladder cancer cell lines and in primary urothelial tumors." (PMID 25344376, 2015). "In the case of certain tumors, as exemplified by breast and bladder cancers, HSPA2 can be detected in tumor but not in the corresponding normal tissue." (PMID 25344376, 2015).
prostate carcinoma (3 papers, 2011 to 2023). A carcinoma that arises from epithelial cells of the prostate gland. "HSPA2 was also found in EVs derived from urine of healthy male donors (n = 8) and prostate cancer patients with different Gleason Scores (n = 16)." (PMID 36959387, 2023). "This study also revealed that the levels of HSPA2 in urinary EVs from healthy donors as well as prostate cancer patients were correlated with EVs markers, especially TSG101." (PMID 36959387, 2023). "Our results also comply with findings showing an insignificant impact of selective siRNA-mediated HSPA2 knockdown on the viability of certain breast, colon, ovarian, and prostate cancer cell lines." (PMID 32987811, 2020). "To elucidate the mechanism of anti-proliferative and pro-apoptotic effects of tNASP depletion in prostate cancer cells we examined HSPA2 ATPase activity." (PMID 21496299, 2011).
bladder urothelial cancer (2 papers, 2013 to 2021). "HSPA2 mRNA was down-regulated in stomach adenocarcinoma, colon adenocarcinoma, bladder urothelial carcinoma, kidney renal clear cell carcinoma, kidney renal papillary cell carcinoma and kidney chromophobe." (PMID 34712697, 2021).
diabetes (2 papers, 2021 to 2024). "By assessing myocardial transcriptomic hits in their circulating protein form, we validated lower ERBB3 and higher HSPA2 in people with diabetes and found these to be associated with LV dysfunction, incident HF, and cardiovascular mortality." (PMID 39180332, 2024). "Higher HSPA2 was associated with older age, female sex, higher BMI, higher prevalence of DM, prior MI and HF, and greater use of a range of cardiovascular and diabetes medications." (PMID 39180332, 2024). "This work found diabetes is characterized by lower Erbb3 and higher Hspa2 mRNA expression in myocardium, with directionally concordant differences in their plasma protein concentration." (PMID 39180332, 2024). "Together with wider evidence we discuss, these data suggest that ERBB signalling and HSPA2 may be important in the development of HF in people with diabetes, and warrant further exploration as biomarkers to target preventative therapies." (PMID 39180332, 2024). "In the whole UKB plasma proteomics cohort, including participants without diabetes, we found lower plasma ERBB3 and higher HSPA2 to be associated with impaired LV contractility, incident HF, and cardiovascular mortality." (PMID 39180332, 2024).
lymph node metastases (2 papers, 2013 to 2015). "Our data revealed that high HSPA2 protein expression was well correlated with lymph node metastasis and predicted worse prognosis." (PMID 23777267, 2013). "Overexpression of HSPA2 was significantly associated with primary tumor, TNM stage, lymph node metastases and recurrence, respectively (all, P <0.05)." (PMID 23777267, 2013).
metastatic tumor (2 papers, 2020 to 2022).
pancreatic adenocarcinoma (2 papers, 2020 to 2022). "Zhai et al7 also noted that HSPA-2 was related to a poor prognosis in tumor angiogenesis and pancreatic adenocarcinoma and played an important role in its progression." (PMID 35703525, 2022). "We have used this antibody in our recent studies on HSPA2 expression and function in epidermal keratinocytes and NSCLC cells; it was also used in one study aimed at evaluating potential value of HSPA2 as a prognostic biomarker in pancreatic adenocarcinoma." (PMID 32560263, 2020).
pancreatic ductal adenocarcinoma (2 papers, 2015 to 2019). An infiltrating adenocarcinoma that arises from the epithelial cells of the pancreas. "Our data revealed that the mRNA expression level of HSPA2 was significantly upregulated in pancreatic ductal adenocarcinoma and its expression was correlated with tumor size, tumor differentiation, TNM stage, lymph node metastasis, and serum CA19-9 levels." (PMID 25890028, 2015).
skin cancer (2 papers, 2022 to 2023). "In their study, Scieglinska et al14 reported observing positive HSPA-2 in keratinocytes in the adjacent epidermis basal layer and infiltrative areas of all skin tumors." (PMID 35703525, 2022).
adenoma (1 paper, 2021). A neoplasm arising from the epithelium. "We compared the invasion-related molecular markers in various subtypes of NF-PitNEts and found that HSPA2 and INSM1 expression was higher in SCAs than SGAs or null cell adenomas (P < 0.0001)." (PMID 33391466, 2021).
bipolar disorder (1 paper, 2009). A disorder of the brain that causes unusual shifts in mood, energy, activity levels and the ability to carry out day-to-day tasks. "Seven genes, APP, ERBB3, FEZ1, HSPA2, SERPINI1, SOX10 and SYN2, display altered expression in studies of schizophrenia or bipolar disorder." (PMID 19300510, 2009).
bronchioalveolar carcinoma (1 paper, 2020). "We established bronchioalveolar carcinoma NCI-H358 cell line and squamous cell carcinoma NCI-H520 cell line with a stable HSPA2 knockdown." (PMID 32987811, 2020).
co-infection (1 paper, 2025). "The downregulation of HSPA2 following co-infection may reflect parasite-induced immune suppression or a shift in energy allocation." (PMID 40943072, 2025).
cognitive decline (1 paper, 2021). "In addition, heat shock-related 70-kDa protein 2 (encoded by HSPA2) has been linked to myelination function and fast cognitive decline." (PMID 34480088, 2021).
colon adenocarcinoma (1 paper, 2021). "The qRT-PCR validation results in vivo showed that HSPA2 was down-regulated in stomach adenocarcinoma and colon adenocarcinoma; HSPA7 and HSPA1A also were down-regulated in colon adenocarcinoma." (PMID 34712697, 2021). "qRT-PCR validation results verified that HSPA2 was down-regulated in stomach adenocarcinoma and colon adenocarcinoma, HSPA7 and HSPA1A also were down-regulated in colon adenocarcinoma tissues." (PMID 34712697, 2021).
cyst (1 paper, 2021). A sac-like closed membranous structure that may be empty or contain fluid or amorphous material. "Immunofluorescence of TOP2A and HSPA2, the genes with high expressions in state 1 cells, showed differential expressions in germ cells of the same cyst in P0.5 ovaries." (PMID 34174788, 2021).
dry eye (1 paper, 2021). "Moreover, based on our current database of RNA-seq, our results suggested that other oxidative-related genes, such as YPEL2 and HSPA2 could become promising treatment targets in dry eye after systematic in vitro and in vivo studies." (PMID 35096875, 2021).
dysplasia (1 paper, 2022). A usually neoplastic transformation of the cell, associated with altered architectural tissue patterns. "The expression of HSPA-2 expression was only observed in the basal layer of adjacent squamous epithelium not containing dysplasia in all the cases." (PMID 35703525, 2022). "The expression of HSPA-2 was only observed in the basal layer of adjacent squamous epithelium not containing dysplasia in all the cases." (PMID 35703525, 2022).
epithelial dysplasia (1 paper, 2022). "Based on this different staining pattern, we consider that the HSPA-2 expression pattern can be extremely helpful in the differential diagnosis when distinguishing epithelial dysplasia in laryngeal biopsies." (PMID 35703525, 2022).
Globozoospermia (1 paper, 2022). Any structural anomaly of the acrosome resulting in a round sperm head. "The relationship between the low expression of HSPA2 and morphological defects could explain pregnancy failure in globozoospermia." (PMID 35163651, 2022).
heart failure (1 paper, 2024). Inability of the heart to pump blood at an adequate rate to meet tissue metabolic requirements. "Participants in the lowest quartile of circulating ERBB3 or highest quartile of circulating HSPA2 had increased incident heart failure and cardiovascular death vs. all other quartiles." (PMID 39180332, 2024). "Kaplan–Meier curves illustrate a higher incidence of heart failure in the lowest quartile of ERRB3 and highest quartile of HSPA2; there were no interquartile differences for NRXN3." (PMID 39180332, 2024).
inflammatory skin disease (1 paper, 2025). Inflammatory skin disorders covers a broad category that includes many conditions ranging in severity, from mild itching to grave medical health complications These disorders are common in people of all ages and races. "Thus, HSPA2 could be implicated in cutaneous disease etiology and may represent a potential target or therapeutic agent in inflammatory skin diseases." (PMID 40287440, 2025). "Testing the efficacy of topically applied HSPA2 encapsulated in nanovesicles via a carrier (cream, patch) could offer a novel approach for treating inflammatory skin diseases." (PMID 40287440, 2025). "Therefore, further research on the role of HSPA2 in the pathogenesis of inflammatory skin diseases is warranted." (PMID 40287440, 2025). "Therefore, our findings suggest that HSPA2 might play a role in the pathogenesis of inflammatory skin diseases." (PMID 40287440, 2025).
ischemia (1 paper, 2022). A hypoperfusion of the BLOOD through an organ or tissue caused by a PATHOLOGIC CONSTRICTION or obstruction of its BLOOD VESSELS, or an absence of BLOOD CIRCULATION. "Upregulated HSPA2 exerted a neuroprotective effect through its regulation of endocytosis in a rat middle cerebral artery occlusion model, and inhibition of HSPA8 would protect against spinal ischemia–reperfusion injury via astrocyte NF-κB/NLRP3 inflammasome pathway." (PMID 36120453, 2022).
keloid (1 paper, 2023). An irregularly shaped, elevated mark on the skin caused by deposits of excessive amounts of collagen during wound healing. "Cross-validation analysis in the LASSO regression model selected the optimal λ value, minimizing error and finding three keloid-related genes: HSPA2, HECW2, and homeobox C9 (HOXC9)." (PMID 37915086, 2023).
keratoconus (1 paper, 2022). A degenerative, structural disorder of the eye, characterized by a cone-shaped protrusion of the cornea. "Among the proteins identified in exosomes, frequently accepted markers of nanovesicles such as CD81 and various Hsp70 species were found, including HSPA2 in both types of exosomes, HSP1B in healthy ones, and HSPA5 and HSPA6 in keratoconus." (PMID 36289615, 2022).